TSC2 (TSC complex subunit 2)
Diseases named in the same sentence as TSC2 in open-access papers (continued):
Sharing a sentence is not in itself a finding about the gene and the disease.
lymphangioleiomyomatosis (continued). "Mutations in TSC1 and TSC2 have been reported in a variety of neoplasms and benign tumors including pulmonary lymphangioleiomyomatosis (LAM), perivascular epitheloid cell tumors (PEComa), urothelial carcinomas, renal cell carcinoma and hepatocellular carcinomas." (PMID 28302097, 2017). "Firstly, the cited work used a cellular model of a lymphangioleiomyomatosis with biallelic inactivation of TSC2, which was a different genetic defect than the one observed in our group." (PMID 27680012, 2016). "Lymphangioleiomyomatosis (LAM) is a rare lung-metastasizing neoplasm caused by the proliferation of smooth muscle-like cells that commonly carry loss-of-function mutations in either the tuberous sclerosis complex 1 or 2 (TSC1 or TSC2) genes." (PMID 26167915, 2015). "Mutations in either the TSC1 gene on chromosome 9q34, or the TSC2 gene on chromosome 16p13.3 cause tuberous sclerosis complex (TSC) and lymphangioleiomyomatosis (LAM)." (PMID 23006675, 2012). "Lymphangioleiomyomatosis (LAM) is a rare, progressive lung disease characterized by neoplastic-like proliferation of abnormal smooth muscle–like cells, primarily driven by mutations in the TSC2 gene." (PMID 40776927, 2025). "Lymphangioleiomyomatosis (LAM) is a rare, almost exclusively female lung disease linked to inactivating mutations in tuberous sclerosis complex 2 (TSC2), a tumor suppressor gene that controls cell metabolic state and growth via regulation of the mechanistic target of rapamycin (mTORC1) signaling." (PMID 29758070, 2018). "Lymphangioleiomyomatosis (LAM) is a rare progressive disease, characterized by mutations in the tuberous sclerosis complex genes (TSC1 or TSC2) and hyperactivation of mechanistic target of rapamycin complex 1 (mTORC1)." (PMID 35181635, 2022). "The aim of our study was to elucidate the landscapes of genetic alterations of TSC1 and TSC2 as well as other possible non-TSC1/2 in Lymphangioleiomyomatosis (LAM) patients." (PMID 31856217, 2019). "Pulmonary lymphangioleiomyomatosis (LAM) is a rare lung disease caused by mutations in the tumor suppressor genes encoding Tuberous Sclerosis Complex (TSC) 1 and TSC2." (PMID 26765535, 2016). "The malignant manifestations of TSC, pulmonary lymphangioleiomyomatosis (LAM) and renal angiomyolipoma (AML), may also occur as independent sporadic perivascular epithelial cell tumor (PEComa) characterized by somatic TSC2 mutations." (PMID 35483879, 2022). "Lymphangioleiomyomatosis (LAM), a progressive pulmonary disease exclusively affecting females, is caused by defects or mutations in the coding gene tuberous sclerosis complex 1 (TSC1) or TSC2, causing the mammalian target of rapamycin complex 1 (mTORC1) activation and autophagy inhibition." (PMID 36543771, 2022). "Additionally, our results indicate that TSC1/TSC2 alterations, including CN-LOH, are nearly universally present in SEGAs, consistent with TSC1/TSC2 molecular findings seen in other TSC-related tumors e.g. renal angiomyolipomas (AMLs) and lymphangioleiomyomatosis (LAM)." (PMID 29221145, 2017). "Tuberous Sclerosis Complex (TSC) and sporadic Lymphangioleiomyomatosis (LAM) are tumor suppressor syndromes sharing the same primary genetic and biochemical features; inactivation of the tumor suppressors TSC1 or TSC2, and aberrant regulation of the PI3K/mTOR pathway." (PMID 30816188, 2019).
breast carcinoma (50 papers, 2006 to 2025). "Using Tuberous Sclerosis Complex 2 (TSC2)-deficient cells, as well as ovarian and breast cancer cell lines, we found that these cells were resistant to ferroptosis." (PMID 40867343, 2025). "Our work reveals that NRF2 and FSP1 contribute to ferroptosis resistance in TSC2-deficient, ovarian, and breast cancer cells." (PMID 40867343, 2025). "Conversely, low levels of TSC1 and TSC2 are associated with an unfavorable prognosis in breast cancer and some other cancers." (PMID 39367202, 2024). "Mutation, down-regulation, and protein inactivation of TSC2 in breast cancer cause over-activation of mTORC1, which leads to treatment resistance and metastasis." (PMID 37251941, 2023). "The HER2-positive breast cancer patient harboring the TSC2 germline nonsynonymous variant c.4349 C > G was resistant to trastuzumab administered during neoadjuvant therapy." (PMID 37160904, 2023). "This suggested that low TSC2 expression was associated with aggressiveness and unfavorable prognosis in patients with breast cancer." (PMID 37251941, 2023). "The results have demonstrated that the TSC2 gene was associated with the risk of overall and ER+ breast cancers (P = 0.009 and 0.012, respectively)." (PMID 37251941, 2023). "HR+/HER2- advanced breast cancer has a higher rate of TSC2 mutations compared to HR+/HER2- early breast cancer." (PMID 37251941, 2023). "In contrast, according to the Cancer Genome Atlas data, the mutation rate of TSC1/TSC2 was only 0.7% (P = 0.0004) in patients with HR+/HER2- early-stage breast cancer." (PMID 37251941, 2023). "HER2-positive breast cancer patients carrying the germline TSC2 nonsynonymous variant c.4349 C > G (p.Pro1450Arg) are resistant to anti-HER2 therapy." (PMID 37160904, 2023). "Consistent with these cell culture findings, our study now provides the first clinical data that implicate TSC2 mutational features in the development of acquired resistance to palbociclib in human breast cancer patients." (PMID 35740538, 2022). "Loss of TSC2 expression and, therefore, abnormally enhanced mTOR activity, have been associated with lung‐metastatic potential in breast cancer." (PMID 34378323, 2021). "However, TSC2 SNP rs181088346 was significantly associated with a reduced overall risk of breast cancer (odds ratio = 0.77, 95% confidence interval = 0.65–0.88, P adj = 0.035)." (PMID 37251941, 2023). "This suggests that HR+/HER2- advanced breast cancer with a higher rate of TSC2 mutations compared to HR+/HER2- early breast cancer may be associated with tumor progression or resistance to therapy." (PMID 37251941, 2023). "There were 143 HR+/HER2- breast cancer samples, and TSC2 was mutated in four (2.8%) of them." (PMID 37251941, 2023). "G3BP1 promotes proliferation of breast cancer cells and in a TSC2-deficient tumor model." (PMID 34778262, 2021). "Indeed, CDK4/6 inhibition was associated with a reduction in TSC2 phosphorylation in HER2-positive breast cancer mouse models and was shown to resensitize tumors to EGFR/HER2 blockade." (PMID 30167080, 2018). "Furthermore, low expression of TSC2 is associated with poor prognosis in breast cancer." (PMID 37251941, 2023). "Thus, the TSC2 gene may be connected with genetic susceptibility of HR+/HER2- breast cancer." (PMID 37251941, 2023). "Single mutations were identified in MEN1 for gastric cancer, MSH6 for colorectal cancer, CDKN2A for pancreatic cancer, and EPCAM/TSC2/GALNT12 for breast cancer." (PMID 38201513, 2023). "In-depth study of TSC2 functions provides significant guidance for clinical applications in breast cancer, including improving the treatment efficacy, overcoming drug resistance, and predicting prognosis." (PMID 37251941, 2023). "In this review, protein structure and biological functions of TSC2 were described and recent advances in TSC2 research in different molecular subtypes of breast cancer were summarized." (PMID 37251941, 2023).
breast carcinoma (continued). "The altered TSC2 gene was observed in both metaplastic breast cancer (a rare special histological type of TNBC) and LAR cohorts (2/17, 2/8, respectively)." (PMID 37251941, 2023). "TSC2-null breast cancer cells are sustained mechanistic targets of rapamycin complex 1 (mTORC1) activity that regulates essential cellular activities." (PMID 37251941, 2023). "Hypermethylation of the promoters of tumor suppressor genes ATM, NOTCH1, NUP98, PALB2, TSC2, and WRN had all previously been associated with WTC exposure and were again observed to be hypermethylated in WTC EHC compared to NYUWHS breast cancer patients." (PMID 35564499, 2022). "Following on from the breast cancer predictions, HRH1 was found overexpressed in Tsc2‐deficient relative to wild‐type MEFs when exposed to serum‐reduced (0.5% FBS) media." (PMID 34378323, 2021). "The results showed that some of the genes related to the prognosis of breast cancer (IKBKB, ATG16L2, CLN3, MBTPS2, TSC2, and CAPN10) had a higher frequency of mutations." (PMID 34457116, 2021). "Gene deletion of AKT1 resulted in reduced cellular migration in vitro, reduced metastasis of HER2-induced breast cancers, and reduced phosphorylation of the tumor suppressor tuberous sclerosis complex 2 (TSC2) in a murine in vivo model." (PMID 33291460, 2020). "On the downside AKT1 decreases migration of breast cancer cells, for instance by regulating TSC2, palladin and EMT-proteins." (PMID 31752925, 2019). "ARD1 prevents mTOR activity and breast cancer cell growth by stabilizing tuberous sclerosis complex 2 (TSC2) to induce autophagy." (PMID 30154412, 2018). "Loss of TSC2 was associated to everolimus response in PDX models of hepatocellular carcinoma and breast cancer patients with low level of LKB1 protein derived greater benefit from everolimus in combination with tamoxifen in the TAMRAD trial." (PMID 27374081, 2016). "High levels of TSC2 were correlated with increased metastasis and reduced survival in breast cancer patients, revealing a protumorigenic role for TSC2." (PMID 21211025, 2011). "Some breast cancers may have active mTORC1 signaling, where the modulation of TSC2 activity may offer additional therapeutic benefits." (PMID 40282469, 2025). "Similarly, models of HER2+ breast cancer have also found that CDK4/6 inhibition suppresses TSC2 phosphorylation and decreases mTORC1 activity." (PMID 40282469, 2025). "Furthermore, the abundance of ARD1 and TSC2 exhibited a significant correlation across various tumor types, particularly in breast cancer, where ARD1 levels notably influenced TSC2 stability and inhibition of the mTOR signaling pathway." (PMID 40026288, 2025). "The low expression of TSC2 is related to the poor prognosis of breast cancer." (PMID 40005880, 2025). "There is also growing evidence that TSC2 plays an essential role in breast cancer." (PMID 37251941, 2023). "Hence, the present review summarizes the functions of TSC2 and recent advances in TSC2 research in different subtypes of breast cancer in order to provide new directions for breast cancer clinical applications." (PMID 37251941, 2023). "Therefore, it is clear that TSC2 plays an inhibitory role in the proliferation of cells in HR+ breast cancer." (PMID 37251941, 2023). "TSC2 acts as an integrator of various signaling cues and regulates cellular metabolism and autophagy through inhibition of mTORC1, which are processes relevant to the progression, treatment, and prognosis of breast cancer." (PMID 37251941, 2023). "This indicates that TSC2 has significant potential in the treatment of HER2-positive breast cancer." (PMID 37251941, 2023). "The functions of PRKAA1, PTK2, and TSC2 in PI3K/signaling governing HER2+ breast cancer development and suppression by PGB-0-ol remain unknown and require further investigation." (PMID 38028209, 2023). "Meanwhile, ARD1 also acetylated and stabilized TSC2 to decrease breast cancer cell growth." (PMID 30154412, 2018).
breast carcinoma (continued). "Relatively low TSC2 expression was found to be significantly associated with lung but not bone metastasis events in the analysis of a seminal breast cancer dataset." (PMID 26167915, 2015). "In addition, depletion of TSC2 in MCF7 breast cancer cells led to a significant gene expression activation of the signature." (PMID 26167915, 2015). "Notably, in breast cancer, relative low expression of hamartin and tuberin (TSC1 and TSC2 products, respectively) is associated with poor clinical outcome, and depletion of tuberin promotes metastasis." (PMID 26167915, 2015). "Therefore, it is important to explore the function of TSC2 in breast cancer." (PMID 37251941, 2023). "Another early study in breast cancer revealed that NAA10 directly interacts with tuberous sclerosis complex 2 (TSC2) and mediates its N-terminal acetylation, resulting in TSC2 stabilization, suppression of mTOR signaling, and induction of autophagy." (PMID 40558489, 2025). "As TSC1/TSC2 complex is an activator of mTORC2 signaling and a repressor of mTORC1 and Rheb is an activator of mTORC1 signaling, this data suggests that mTORC2 signaling may be more prominent in ERα+ and mTORC1 signaling may be more prevalent in ERα− breast carcinomas." (PMID 25283550, 2014). "More recently, it has been shown that aberrant expression of TSC1 and TSC2 may be present in breast cancers, renal carcinoma, transitional cell carcinoma, basal cell carcinoma, squamous cell carcinoma and shagreen patches and may serve as a prognostic marker in breast cancer." (PMID 16412252, 2006). "Enrichment difference analysis of the genes showing changes after OHT treatment revealed known breast cancer oncogenes such as HDAC3, UBE2C and CPSF7 among the depleted genes and reported breast cancer suppressors such as CSK, SPRED2 and TSC2 among the enriched genes." (PMID 38914552, 2024). "Data from a 10-year follow-up study have indicated that tumor tissues from breast cancer patients who relapsed or died had significantly low levels of TSC2 compared to patients who did not experience recurrence (P = 0.03 and 0.05, respectively)." (PMID 37251941, 2023). "As 3D culture could better reflect HER signaling conditions and trastuzumab action in vivo, it will be employed in future studies to further assess the trastuzumab resistance mechanism in TSC2-MT and HER2-positive breast cancer cell lines." (PMID 37160904, 2023). "The PDK1-SGK1 axis has been characterized as a drug-resistant mechanism of the PI3Kα inhibitor alpelisib in breast cancer, in which mTORC1 is activated via direct phosphorylation and inhibition of TSC2, a negative mTORC1 regulator, by SGK1." (PMID 36457711, 2022). "Overall, we found evidence for associations with breast cancer risk with single SNPs in 2 genes (RFWD2 and TSC2) among women of European descent, but neither remained statistically significant after correction for multiple testing." (PMID 30601841, 2019). "Previous investigations had reported that TSC2, ARID1A, AXIN1, CASP8, CDH1, and ASXL1 could play roles in tumor suppression in diverse cancer types, including breast cancer." (PMID 29414922, 2018). "For example, the experiment by Sokolosky GSK-3β activity could result in the altered chemosensitivity of MCF-7 breast cancer cells to ADR through regulation of the PI3K/Akt/mTORC1 pathway by phosphorylating signaling molecules such as PTEN and TSC2." (PMID 26066793, 2015). "Sokolosky’s experiment showed that inhibition of GSK-3β activity could result in altered chemosensitivity of MCF-7 breast cancer cells to ADR through regulation of PI3K/Akt/mTORC1 pathway activity by phosphorylating signal molecules such as PTEN and TSC2." (PMID 26066793, 2015). "However the key components of the pathway, such as TSC1/TSC2 and mTORC1, have not been well investigated in normal mammary development, though their roles in breast cancer development have been known better." (PMID 26795955, 2016).
breast carcinoma (continued). "Extensive panel testing covering more than 40 genes is being increasingly marketed, but the diagnostic yield and action-ability remains questionable particularly for candidate genes such as TSC2 / PALLD which may not be relevant to patients with suspected hereditary breast cancer." (PMID 30875412, 2019).
hamartoma (45 papers, 2008 to 2025). A benign and excessive tumor-like growth of mature cells and normal tissues which grow in a disorganized pattern. "TSC is an autosomal dominant neurocutaneous disorder caused by mutations in TSC1 or TSC2, clinically characterized by the development of hamartomas across multiple organ systems." (PMID 41142004, 2025). "In a study of 111 TSC-associated tissues, two-thirds of hamartomas were found to contain two hits to TSC1/TSC2, including most SEGAs, SENs, and renal angiomyolipomas, as well as 35% of tubers." (PMID 38540392, 2024). "Tuberous sclerosis complex (TSC) is a multisystem monogenetic disorder caused by mutations in either TSC1 or TSC2 and is characterized by hamartoma development in several organs, including the brain, kidneys, lungs, heart, eyes, and skin." (PMID 34709498, 2022). "It is caused by a mutation in either the TSC1 or TSC2 gene and is characterized by the development of tumours or hamartomas in many organs." (PMID 36362447, 2022). "Generally, 30 to 40% of individuals with TSC are assumed to be impacted by hamartomas, with TSC2 mutations conferring a particularly higher risk." (PMID 31964424, 2020). "TSC1 and TSC2 variants are thought to result in a loss of function, leading to multiple organ hamartias and hamartomas." (PMID 32211034, 2020). "It occurs due to inactivating mutations in either of the two genes, TSC1 and TSC2, following a second hit in a tumor suppressor gene in most hamartomas." (PMID 28968464, 2017). "Other examples include TSC2, where mutations have been linked to the development of hamartomas in multiple organs; and ATAD5, the somatic mutations of which were identified in endometrial tumors." (PMID 27150584, 2016). "Tuberous sclerosis complex (TSC) is an autosomal dominant disorder due to mutations in either TSC1 or TSC2 that affects many organs with hamartomas and tumors." (PMID 23696872, 2013). "Tuberous sclerosis complex (TSC) is a human genetic disorder in which loss of either TSC1 or TSC2 leads to development of hamartoma lesions, which can progress and be life-threatening or fatal." (PMID 22363765, 2012). "Loss of TSC1/TSC2 in TSC hamartomas leads to both activation of mTORC1, as well as feedback inhibition of AKT, through downregulation of IRS and PDGFR expression and other mechanisms." (PMID 19527517, 2009). "Tuberous sclerosis complex (TSC), a tumor syndrome caused by mutations in TSC1 or TSC2 genes, is characterized by the development of hamartomas." (PMID 18958173, 2008). "Mutations in the TSC1 and TSC2 genes result in the constitutive hyperactivation of the mammalian target of the rapamycin (mTOR) pathway, contributing to the growth of benign tumors or hamartomas in various organs." (PMID 39852149, 2025). "In support of this notion, hamartomas associated with mutations in TSC1 or TSC2 (tuberous sclerosis complex 1 and 2) genes in humans have been phenocopied in zebrafish by the generation of mosaic embryos that carry wild-type and tsc2 (vu242/vu242) mutant cells." (PMID 29716894, 2018). "Loss of Tsc1/Tsc2 results in excess cell growth that eventually forms hamartoma in multiple organs." (PMID 26795955, 2016). "Loss of either TSC1 or TSC2 in TSC hamartomas leads to activation of mTORC1 and suppression of AKT." (PMID 19527517, 2009). "However, efforts to model hamartomas have largely been unsuccessful, in part due to the early lethality of homozygous germline mutations in Pten and other hamartoma-associated genes, such as tuberous sclerosis genes (Tsc1/Tsc2)." (PMID 29716894, 2018). "Tuberous sclerosis complex (TSC) is an autosomal dominant genetic disease characterized by the presence of hamartomas affecting multiple systems in the body, caused by loss-of-function mutations in the TSC1 or TSC2 genes." (PMID 39119187, 2024).